CARD9 (caspase recruitment domain family member 9)
Diseases named in the same sentence as CARD9 in open-access papers (continued):
Sharing a sentence is not in itself a finding about the gene and the disease.
colitis (63 papers, 2016 to 2025). Inflammation of the colon. "This is surprising as, in the other way around, the transplantation of a Card9–/– microbiota in WT mice was sufficient to increase colitis susceptibility, suggesting a dominant effect of detrimental genotype and microbiota in this model." (PMID 38649950, 2024). "We show that Card9 modulates the susceptibility to DSS-induced colitis in both microbiota-dependent and independent manners." (PMID 38649950, 2024). "We previously showed that Card9−/− mice microbiota contributes to susceptibility to DSS-induced colitis." (PMID 38649950, 2024). "Here, we demonstrated that Card9 modulates the susceptibility to DSS-induced colitis in both microbiota-dependent and microbiota-independent manners." (PMID 38649950, 2024). "Recently, we demonstrated that the transfer of Card9–/– mice microbiota to GF WT recipient mice was sufficient to recapitulate the defective IL-22 activation and increased colitis susceptibility observed in Card9–/– mice." (PMID 38649950, 2024). "Card9−/− mice have an enhanced susceptibility to dextran sodium sulfate (DSS)-induced colitis and an increased load of gut-resident fungi." (PMID 38649950, 2024). "To compare the impact of Card9 deletion and the gut microbiota on colitis susceptibility, we colonized adult GF Card9−/− or GF WT mice with the microbiota of WT mice (WT ➔ GF Card9−/− and WT ➔ GF WT) and exposed them to DSS." (PMID 38649950, 2024). "Card9-/- mice, which are more susceptible to colitis, have a reduced ability to activate AhR, which is associated with decreased indole acetic acid levels." (PMID 35237276, 2022). "Host deficiency in Card9 or carrying CARD9 risk alleles results in a microbiome with reduced capability to metabolize tryptophan into Ahr ligands, resulting in increased colitis susceptibility in the mouse model." (PMID 35534699, 2022). "Card9−/− mice appear to be more susceptible to colitis, have dysbiosis, and a reduction in colonic IL-22 expression." (PMID 34362137, 2021). "Card9-deficient mice exhibit reduced expression of IL-22 in the colon, and are more susceptible to colitis." (PMID 34062869, 2021). "After DSS-induced colitis in caspase recruitment domain-containing protein 9 (Card9) knockout mice dysbiosis was associated with reduced IAA levels, reduced IL-22 production, and higher susceptibility to inflammation." (PMID 33562721, 2021). "Specifically, one of the numerous colitis susceptibility factors, Card9-signaling has been implicated in intestinal immune responses and the maintenance of homeostasis after epithelial injury and bacterial infection in mice." (PMID 34769321, 2021). "CARD9 is a susceptibility gene for inflammatory bowel disease, and it has been shown that CARD9 promotes recovery from colitis through the production of IL-22." (PMID 34362137, 2021). "The adaptor protein Card9, the downstream signal molecules of CLRs, was reported to attenuate the progression of colitis-associated colon cancer by restricting the expansion of MDSCs." (PMID 34480018, 2021). "Mice deficient in Card9 (the downstream molecule of CLRs) were more susceptible to colitis-associated cancer via promoting the expansion of MDSCs." (PMID 34480018, 2021). "Sensing of commensal gut fungi through the Card9–Syk signaling axis promotes inflammasome activation and maturation of IL-18, which plays a protective role in colitis and colitis-associated carcinogenesis." (PMID 32550001, 2020). "CARD9, as a susceptibility factor for colitis, mainly induces the intestinal mucosal immune response and mediates gut microbiota composition and metabolism." (PMID 31696662, 2020). "Transfer of CARD9-deficient microbiota into wild type or germ free mice, increased their susceptibility to colitis, with IL-22 being the most highly downregulated gene compared to controls." (PMID 32957545, 2020). "CARD9-deficient mice exhibited a defect in epithelial regeneration and a significant delay in weight gain during the recovery phase after acute colitis." (PMID 30906296, 2019).
colitis (continued). "Under steady-state conditions, the fungal burden is increased in CARD9-deficient mice, and during colitis, the fungal microbiome changes more substantially in CARD9-deficient mice than in wild-type mice." (PMID 30906296, 2019). "Interestingly, Card9-deficient mice were found to be susceptible to colitis due to impaired tryptophan metabolism, mitigating the formation of aryl hydrocarbon receptor (AHR) ligands." (PMID 40671790, 2025). "Moreover, we also demonstrated that the transfer of Card9−/− mice microbiota to wild-type (WT) germ-free (GF) recipients was sufficient to recapitulate the defective IL-22 activation and the increased colitis susceptibility observed in Card9−/− mice." (PMID 38649950, 2024). "CARD9 deficiency in murine colitis models has shown interesting, yet somewhat conflicting, results." (PMID 37998910, 2023). "CARD9 deletion in DCs attenuates the progress of Lyn deficiency-associated colitis in mice." (PMID 35432375, 2022). "For example, human CARD9 deficiency contributes to chronic mucocutaneous candidiasis and invasive Candida infections in the central nervous system or digestive tract (e.g., meningoencephalitis, colitis)." (PMID 35619716, 2022). "Moreover, transfer of the Card9-/- microbiota to germ-free mice leads to increased susceptibility to colitis and lower levels of IL-22, indicating that the unbalanced microbiota drives the immune dysregulation." (PMID 36144238, 2022). "However, in Lyn deficiency mice, CARD9 promotes the development of colitis because of increased production of cytokines (TNF-α and IL-6)." (PMID 35432375, 2022). "Gut dysbiosis in Card9-deficient mice decreases AhR activation and hinders recovery from colitis." (PMID 34062869, 2021). "M. restricta mainly triggers innate inflammation through CARD9 and is recognized by anti-fungal anti-bodies in patients with CD; it will produce strong inflammatory cytokines from innate cells carrying IBD-related CARD9 polymorphisms and aggravate colitis in mice model." (PMID 34970585, 2021). "In five additional patients, with CARD9 gene mutations, who all were born to consanguineous parents of Arabic origin, an association of CARD9 gene mutations with tissue culture proven Candida colitis was described." (PMID 29371502, 2018). "Card9–/– mice seem more susceptible to experimentally-induced colitis and typified by defective IFNγ and Th17 responses, as well as reduced transcription of the mucosal chemokine CCL20; signifying the critical importance of CARD9 in the maintenance of epithelial immunostasis." (PMID 26593288, 2016). "Moreover, Card9−/− mice has an altered microbiota with increased load of gut-resident fungi, and reduced IL-22 production, and the transfer of microbiota from knockout mice to wild-type germ-free mice increases their susceptibility to colitis." (PMID 30008619, 2018). "First, we detected the expression of CARD9 in primary cDC2 isolated from mice with colitis treated with WT-EVs and ΔPMA1-EVs." (PMID 39886799, 2025). "Using germ-free models, we proved the direct contribution of Card9 gene in colitis recovery, through the induction of IL-22, REG3β, and REG3, independently of the microbiota." (PMID 38649950, 2024). "CARD9 expression in gastrointestinal tract neutrophils regulates gut microbiota and resistance to gastrointestinal tract inflammation and colitis." (PMID 39457699, 2024). "Card9 gene directly contributes to recovery from dextran sodium sulfate (DSS)-induced colitis by inducing the colonic expression of the cytokine IL-22 and the antimicrobial peptides Reg3β and Reg3γ independently of the microbiota." (PMID 38649950, 2024). "In a previous study, we showed that CARD9 mediates recovery from colitis through the production of IL-22, a cytokine with well-known effects on intestinal homeostasis and barrier function." (PMID 38649950, 2024).
colitis (continued). "CARD9 promotes recovery from colitis by promoting AhR ligands and IL-22 production.Host genes affect the composition and function of the gut microbiota, altering the production of microbial metabolites and intestinal inflammation." (PMID 39767818, 2024). "The defect in the intestinal immune response induced by Card9 gene deletion raises the question of Card9−/− microbiota’s contribution to the hypersusceptibility of WT ➔ GF Card9−/− mice to colitis." (PMID 38649950, 2024). "To examine the mechanisms responsible for this defect, we compared the colon transcriptomes of GF WT and GF Card9−/− during the course of the colitis." (PMID 38649950, 2024). "In line with this, Card9 expression, an essential regulator of intestinal epithelial wound healing in the context of colitis and member of the CBM signalosome, was significantly upregulated during intestinal inflammation." (PMID 37108564, 2023). "Analysis of a DSS time course RNA-seq dataset further revealed increased expression of Malt1 and the CBM complex protein Card9 during active colitis." (PMID 37108564, 2023). "In one study, CARD9-deficient mice displayed reduced Th1 and Th17 cytokine responses to DSS colitis with an increased intestinal fungal burden." (PMID 37998910, 2023). "CARD9 was reported to impact colitis by altering the gut microbiota metabolism of Trp into AhR ligands." (PMID 36817692, 2022). "Treatment with FICZ also improved DSS-induced colitis severity in Card9−/− mice and restored colon IL-22 production and antimicrobial peptides." (PMID 36014759, 2022). "The results demonstrated that SD leads to reductions in plasma melatonin levels and colonic Card9 expression and consequent occurrence of colitis and gut microbiota disorder, especially the downregulation of Faecalibacterium and butyrate levels." (PMID 34769321, 2021). "CARD9 is a susceptibility gene for IBD that modulates the immune response against microorganisms and promotes recovery from colitis by inducing IL-22 production." (PMID 33562721, 2021). "Consistently, IAA levels were reduced in Card9−/− mice and the transfer of Card9−/− intestinal microbiota to germ-free wild type mice was sufficient to impair IL-22 activation and to increase the sensitivity to colitis." (PMID 34362137, 2021). "CARD9 knockout mice exhibit altered tryptophan metabolism of gut microbiota, accounting for their inability to produce AhR ligands, thereby mediating colitis in Card9(-/-) mice." (PMID 34747326, 2021). "Meanwhile, colonization of Candida species as seen in Card9−/− mice also reduced the populations of tryptophan-metabolizing bacteria, including lactobacilli, which intensify the severity of colitis in Card9−/− mice." (PMID 32322167, 2020). "In the mice model of colitis, CARD9 knockout mice had increased antifungal antibodies, and the severity of colitis was mitigated upon antifungal treatment, suggesting the protective role of CARD9 signaling against fungi." (PMID 32322167, 2020). "In DDS‐induced colitis, CARD9 also had a key role in shaping the ecosystem of bacteria and fungi in the gut." (PMID 31696662, 2020). "Caspase recruitment domain family member 9 (CARD9) is a susceptibility gene for IBD, and Card9 (-/-) mice are more susceptible than are wildtype mice to colitis." (PMID 31772949, 2019). "CARD9 knockout mice exhibited downregulation in IL-22 signalling, resulting in impaired recovery from colitis when compared to wild-type mice." (PMID 30850234, 2019). "Immune recognition of Malassezia occurs specifically through CARD9 in the gut, and knocking out CARD9 in mice abrogates colitis symptoms following exposure to Malassezia." (PMID 31396143, 2019). "Based on the association of CARD9 SNPs with IBD susceptibility, several research groups have started to investigate the role of CARD9 in murine models of experimental colitis." (PMID 30906296, 2019). "It has been demonstrated that CARD9 promotes recovery from colitis through activation of the IL-22 pathway." (PMID 30008619, 2018).
colitis (continued). "CARD9 is also known to be involved in the immune response against microorganisms and was recently shown to have a protective effect in colitis by modulating the microbial metabolism of tryptophan." (PMID 27651359, 2016). "We first questioned whether Card9 gene does contribute to colitis recovery in a gut microbiota-independent manner by exposing GF WT and GF Card9−/− mice to DSS." (PMID 38649950, 2024). "Importantly, CARD9 is also associated with inflammatory bowel disease, and studies using Card9-deficeint mice showed that CARD9 has protective roles against DSS-induced colitis." (PMID 39542253, 2024). "CARD9 promotes recovery from colitis by promoting AhR ligands and IL-22 production." (PMID 39767818, 2024). "CARD9 promotes colitis recovery by increasing the production of IL-22." (PMID 39408347, 2024). "On the other hand, Card9 is required for regulating the microbiota capacity to produce AhR ligands, which leads to the production of IL-22 in the colon, promoting recovery after colitis." (PMID 38649950, 2024). "The microbiota from Card9(−/−) mice fails to metabolize Trp into metabolites that act as AhR ligands, and is more susceptible to colitis." (PMID 39767818, 2024). "A recent study found that CARD9 expression in neutrophils protects against colitis caused by DSS but not in epithelial or CD11c+cells." (PMID 36643579, 2023). "Other studies also suggest that Trp plays a role in the recovery of colitis and in the function of intestinal homeostasis by caspase recruitment domain family member 9 (Card9), calcium-sensing receptor (CaSR), and aryl hydrocarbon receptor (AHR) ligands in the intestine." (PMID 35747264, 2022). "Transferring the intestinal flora from CARD9-null mice to wild-type germ-free mice is proven to promote colitis and reduce IL-22 production, because the microbiota in CARD9-null mice is unable to metabolize tryptophan into the ligands of aryl hydrocarbon receptor (AHR)." (PMID 35619716, 2022). "CARD9 can promote colitis recovery through up-regulation of IL-12 secretion." (PMID 35432375, 2022). "Additionally, GWAS studies in IBD patients have identified mutations impacting IL-22 pathways, especially in the Card9 gene sensing type-C lectins, as also witnessed in Card9 deficient mice, prone to DSS-induced colitis." (PMID 34122415, 2021). "Furthermore, Candida tropicalis, among other fungal species, was shown to protect against colon cancer through CARD9 signaling in intestinal myeloid cells (myeloid-specific deletion of Card9 and Syk in mouse models of colitis and tumorigenesis)." (PMID 31813764, 2020). "It has been described that the intestinal microbiota from CARD9 deficient mice failed to metabolize Trp into AhR ligands, increasing susceptibility to colitis and decreasing epithelial cell proliferation and increased apoptosis." (PMID 32957545, 2020). "Together, these experimental studies revealed that CARD9 signaling within the myeloid compartment affects epithelial regeneration during the recovery from colitis by triggering ILC and TH17 responses, in part by directing the microbiota toward AHR ligand-producing species." (PMID 30906296, 2019). "Moreover, the gut microbiota of NOD2-/- and CARD9-/- mice has pro-inflammatory effects by itself, because it worsens the colitis severity when transferred to germ-free wild type mice." (PMID 30849075, 2019). "Transfer of the CARD9 knockout mouse microbiota to germ-free wild type mice resulted in an exacerbation of colitis, to a similar degree as CARD9 knock out mice – suggesting a causative, rather than correlative, relationship between the microbiome and IL-22 mediated inflammation." (PMID 30850234, 2019). "CARD9 promotes recovery from colitis by stimulating interleukin (IL)-22 production." (PMID 30060580, 2018). "Furthermore, a recent research indicates that Card9, a susceptibility gene of IBD, promotes the recovery of colitis by metabolizing Trp into AHR ligands to activate IL-22 signaling pathway in innate immune response." (PMID 29682569, 2018).
colitis (continued). "For example, the microbiota of mice deficient in caspase recruitment domain family member 9 (CARD9) failed to metabolize tryptophan that increased host susceptibility to colitis." (PMID 28919884, 2017). "Moreover, the adaptor protein CARD9 was critical in PMA1-containing EV-induced colitis, and CARD9-deficient DCs did not induce TH17 cell differentiation or IL-17A production." (PMID 39886799, 2025). "However, the lack of CARD9 is identified to enhance susceptibility to colitis and colitis-associated colon cancer, due to the impaired fungi-neutralizing function of macrophages that leads to the increased accumulation of MDSC." (PMID 34689842, 2021). "Malassezia also exacerbated colitis in a DSS-induced colitis mouse model, which required functional CARD9." (PMID 40511923, 2025). "Mice with knockout for caspase recruitment domain-containing protein 9 (Card9) and DSS-induced colitis showed reduced levels of indole derivative indoleacetic acid and a decreased ability of microbiota to activate AhR." (PMID 38543132, 2024). "At day 12, Tnf-α expression was significantly higher in GF Card9−/− mice compared to GF WT mice, which could reflect the delayed colitis recovery in the absence of Card9." (PMID 38649950, 2024). "Interestingly, some evidence suggests that CARD9 may play a protective role against colitis and CRC through the SYK-CARD9–Il-18 axis." (PMID 34842660, 2021). "To date, no GWAS has shown CARD9 to be a risk allele for RA in humans, but it is an interesting model gene which has relevance in other autoimmune diseases including inflammatory bowel disease (IBD), ankylosing spondylitis, IgA nephropathy and colitis." (PMID 30850234, 2019). "It has been confirmed that, compared with the negative group, Malassezia colonization can induce CARD9-S12N polymorphism and strongly enhance the release of cytokines such as IL-10 or tumor necrosis factor alpha (TNF-α) in either wild-type (WT) or Card9−/− colitis mice." (PMID 35309351, 2022). "Neutrophils also express the IBD-protective gene caspase recruitment domain 9 (Card9), which provides them with the capacity to protect against DSS-induced colitis; a lack of CARD9 enhances mitochondrial dysfunction and ROS generation, leading to neutrophil apoptosis and increased inflammation." (PMID 36675038, 2023).